DNMT1 (DNA methyltransferase 1)
Diseases named in the same sentence as DNMT1 in open-access papers (continued):
Sharing a sentence is not in itself a finding about the gene and the disease.
tumor (continued). "Therefore, to evaluate the effect of DNA demethylation in the absence of cellular toxicity, we next performed lentivirus-mediated knockdown of the major DNA methyltransferase, Dnmt1, in intestinal tumor organoids." (PMID 27143627, 2016). "DNMT3B and DNMT1 studied regions were largely hypomethylated both in blood and tumor tissue DNA." (PMID 27999265, 2016). "Because the promoter methylation of E2F1-dependent proapoptotic genes is a step in apoptotic defense mechanisms, the simultaneous inhibition of both SET9 and DNMT1 in the presence of DNA damage may be required to favor the tumor-suppressor function of E2F1." (PMID 27054335, 2016). "The expression of DNMT1 also significantly correlated with perineural invasion, tumor differentiation, and staging, suggesting that DNMT1 could be prognostic markers for PDAs." (PMID 27999365, 2016). "Regarding the DNMTs, the writers of DNA methylation reactions, in this study only DNMT3A showed increased methylation levels in tumor tissue, comparable to those found in adjacent thymic tissue, with respect to blood; the other two DNMTs genes, DNMT1 and DNMT3B, resulted hypomethylated." (PMID 27999265, 2016). "Thus, Dnmt1 seems to possess an oncogenic function by promoting cellular survival of both normal and tumor cells." (PMID 27563627, 2016). "However, there is also evidence that Dnmt1 can play a tumor suppressor role in prevention of T-cell lymphomas." (PMID 27563627, 2016). "Studies have shown that DNMT1 is abnormally expressed in many tumor types." (PMID 25580536, 2015). "In addition, the HCV core protein appears able to up-regulate the levels of DNMT1 and DNMT3b and to induce promoter hypermethylation of tumor suppressor genes like E-cadherin and p16, resulting in down-regulation of their expression." (PMID 26576645, 2015). "Thus, overexpression of DNMT1 results in epigenetic changes of tumour suppressor genes and ultimately results in tumourigenesis." (PMID 25598321, 2015). "The inhibition of DNMT1 by grifolin leads to reactivation of tumor-suppressor gene expression that could have an important impact on tumor invasion and metastasis." (PMID 26516701, 2015). "ChIP analysis revealed that GLI1 binds to the DNMT1 promoter suggesting that GLI1 may regulate tumor-related genes through DNMT1 expression." (PMID 26633513, 2015). "A similar divergence in proliferative response to DNMT1 depletion may account for the observation that DNA methylation inhibitors induce CG gene activation more efficiently in tumor cells than in normal cells." (PMID 26504497, 2015). "However, despite the crucial character of the integrity of the DNMT1/PCNA/UHRF1 complex, the integrity of other DNMT1 including complexes plays a major role in the inheritance of DNA methylation and in tumor development and progression." (PMID 24637615, 2014). "For example, miR-152 acts as a tumor suppressor via suppression of DNMT1." (PMID 24592273, 2014). "We assayed the expression levels of DNMT1 enzyme mRNA in 125 tumor and adjacent normal tissues." (PMID 25107489, 2014). "Nonetheless, they may exist in some GBM patients as DNMT1 has been shown to be a potential GBM therapeutic target whose inhibition leads to an increase of several tumor suppressor genes." (PMID 25551752, 2014). "Cellular IL-6, a bridge molecule between chronic inflammation and carcinogenesis, could promote colonic tumorigenesis through DNMT1-mediated tumor suppressor gene hypermethylation." (PMID 24675762, 2014). "Consistent with our observations regarding curcumin’s ability to inhibit tumor growth in vivo and down-regulate DNMT1 expression in vitro and ex vivo, we found that decreased levels of DNMT1 protein and mRNA were expressed by tumor cells isolated from curcumin-treated mice." (PMID 23457487, 2013).
tumor (continued). "This curcumin-mediated down-regulation of DNMT1 expression was concomitant with p15INK4B tumor suppressor gene reactivation, hypomethylation of the p15INK4B promoter, G1 cell cycle arrest, and induction of tumor cell apoptosis in vitro." (PMID 23457487, 2013). "Consequently, we distinguish between among the neutral-tumorigenic-specific inhibition of DNMT1/protein-x interaction and the tumor suppressor-like neutral-tumorigenic-specific inhibition of DNMT1/protein-x interaction." (PMID 23809695, 2013). "In addition, knocking down DNMT1 with antisense oligonucleotides inhibits neoplasia in cell culture and in mouse tumor models." (PMID 24236046, 2013). "Our data indicate that the specific inhibition of the DNMT1/DMAP1 interaction acts as a tumor suppressor-like event since the disruption of the DNMT1/DMAP1 interaction increased TMZ + irradiation-induced cell death without promoting the initiation and progression of tumorigenesis." (PMID 23809695, 2013). "Furthermore, evidence for induction of expression of DNMT1 by the HPV oncogenes E6 and E7 adds to a body of supporting evidence for viral regulation, in particular for tumour viruses, of DNMT." (PMID 23189137, 2012). "DMAP1 is known to form a complex with DNMT1 and repress transcription in tumor cells." (PMID 23049944, 2012). "Moreover, expression of DNMT1 protein was higher in the patients whose tumor occurred in single side than that of patients whose tumor occurred in both sides (Pearson Chi-Square test, P = 0.010)." (PMID 22768205, 2012). "In addition, DNMT1 was found deregulated in different human tumors suggesting its involvement in tumor initiation/progression." (PMID 22305267, 2012). "In addition, our data showed that expression of DNMT1 protein was relevant with the localization of the tumor." (PMID 22768205, 2012). "A nearly identical frequency of concordant and discordantfindings was obtained by analyzing the TCGA database (p<0.0001).Expression of DNMT1 and DNMT3b was strongly upregulated in tumor tissue, butnot correlated with MGMT promoter methylation and MGMT mRNAexpression." (PMID 21365007, 2011). "The exact mechanism of this observation remains unclear, but variables involved in the signal pathway including tumor expression of DNMT1, TGF-β1, and p-ERK may be useful in predicting clinical outcome following radical prostatectomy." (PMID 21980391, 2011). "Indeed, that its is following a DNA hypomathylation strategy (inhibition of the Dnmt1 expression or treatment (5aza) or by comparing non tumor cells with tumor cells, the number of Dnmt1/PCNA interactions echoes the degree of DNA methylation." (PMID 21470401, 2011). "There are also reports that the high DNMT1 activity would promote tumor cell proliferation." (PMID 20119531, 2009). "The exact nature of the defect in methylation machinery of tumour cells remain unclear; however, it may be related to the expression of DNA methyltransferases (DNMTs), primarily DNMT1, DNMT3a, and DNMT3b." (PMID 18414412, 2008). "The DNMT1 or DNMT 3B can be considered as a target for epigenetic therapy in human tumor." (PMID 27994704, 2008). "Somatic DNMT mutations have not so far been described in human tumours, although DNMT1 is located in 19p13.3, a region of common loss of heterozygosity in human tumours." (PMID 16404435, 2006). "Because covalent trapping of DNMT1 on DNA has been shown to induce DNMT proteasomal degradation, we assessed whether oral FdCyd-THU therapy yielded changes in tumor DNMT1 levels via IHC analysis of baseline (pre-dose) and on-treatment (Cycle 1 Week 3; C1W3) biopsy specimens." (PMID 41428220, 2025). "The high expression of DNMT1 in tumor cells was previously linked to the binding of MYC to the DNMT1 promoter region and subsequent activation of its transcription, where DNMT1 can be further recruited by enhancer of EZH2 to methylate the promoter sequence of tumor suppressors." (PMID 40317882, 2025).
tumor (continued). "However, the precise mechanism governing the self-renewal and tumor growth of LCSLCs through the interaction of DNMT1 and miR-152 remains unclear." (PMID 38622665, 2024). "Furthermore, silencing DNMT1 effectively inhibited tumor growth." (PMID 38755637, 2024). "EZH2-mediated DNA methylation associated with DNMT1 and H3K27me3 may inhibit the expression of the type 1 T helper cell (TH1) chemokines CXCL9 and CXCL10, as well as the subsequent transport of effector T cells to the tumor microenvironment." (PMID 38665224, 2024). "However, sh-DNMT1 tumor-bearing mice exhibited a slightly greater level of p-GSK3β than nontreated xenografted mice, suggesting that glycogen depredation in sh-DNMT1 tumors themselves may also trigger compensatory liver glycogen metabolism to a certain extent." (PMID 38755637, 2024). "In addition, we have found that expression and DNA methylation of SCARA5 could be used in solid and liquid biopsies as a surrogate indicator of tumor G9a/DNMT1 activity." (PMID 39488528, 2024). "While DMBA led to neoplasia and hyperplasia in breast tissues, the administration of TQ to rats prevented these histological alterations in breast tissues and reduced DMBA carcinogenicity in rats, and these inhibitory effects were associated with a decrease in DNMT1 expression." (PMID 38257347, 2024). "Furthermore, miR-152-3p may upregulate SOS1 by activating DNMT1, thereby promoting self-renewal and tumor growth in LCSLCs." (PMID 38622665, 2024). "Moreover, it has been revealed that EA could suppress DNA methyl transferase 1 (DNMT1) which has a key role in the hypermethylation of tumor suppression of genes resulting in diseased conditions." (PMID 38107139, 2023). "Moreover, transcriptomic analysis of tumor-specific T cells in early malignant lesions revealed upregulation of DNA and histone modifying enzymes, including DNMT1, DNMT3B, EZH2, among others, indicating early involvement of the epigenetic machinery in driving the dysfunctional state." (PMID 36627707, 2023). "The trend of Pdcd1 and Dnmt1 gene upregulations was increasing along with the progression of liver damage from 3 to 12 months of age, representing the natural history of hepatocarcinogenesis from early hepatic damage, inflammation, dysplasia, and finally neoplasia." (PMID 37686163, 2023). "Hence, the reactivation of expression of tumor suppressors is ascribed to the fact that decitabine and azacitidine were more effective for demethylating DNA and generating accessible chromatin when DNMT1 was knocked down." (PMID 37045940, 2023). "Inhibited by TF MED17, target gene DNMT1 undergoes a DNA demethylation reaction, not only weakening its carcinogenicity but also contributing to a gradual slowdown of the cell proliferation rate and a promotion of apoptosis, which plays a crucial role prior to tumor cell metastasis." (PMID 35164166, 2022). "In addition, our results indicated that decreased Dnmt1 and Dnmt3a expression abrogates promoter CpG methylation and depresses inflammatory Casp1 and Casp11 as well as pyroptotic executor Gsdmd to transcriptionally prime Mll4−/− tumor cells for pyroptosis." (PMID 36323669, 2022). "The activity of DNMT enzymes is generally reduced in global hypomethylation, but parallelly, the activity of the DNMT1 enzyme may increase, leading to the hypermethylation of CpG islands of the tumor suppressor genes, silencing them—and thus increases the risk of carcinogenesis or malignancy." (PMID 35215560, 2022). "Silencing of tumor suppressors and DNA repair enzymes by aberrant hypermethylation is seen in many cancers, and the DNMT1 inhibitors azacitidine and decitabine are used to exploit this fact in hematologic cancers to demethylate suppressed promoters, thereby reactivating silenced tumor suppressors." (PMID 35158795, 2022). "Therefore, the relationship BRAFv600e-DNMT1 found in our study sharing this common tumor feature." (PMID 35048062, 2021).
tumor (continued). "Therefore, we hypothesized that the PPARA agonist, fenofibrate, could reduce the content of DNMT1 and rescue the expression of methylation-silenced tumor suppressor genes." (PMID 33959155, 2021). "Moreover, downregulation of DNMT1 in human tumor xenografts reduced in vivo tumor growth." (PMID 33941772, 2021). "Additionally, our data reported that depleted HOTAIR or DNMT1 reduced the proliferation, colony formation, invasion, migration, as well as increased apoptosis rate of CML cells, while low expression of HOTAIR or decreased DNMT1 reduced the volume and weight of tumor in mice injected with CML cells." (PMID 33941772, 2021). "Because DNMT1-mediated methylation downregulated FOXO3a expression, we next tested whether pharmacological inhibition of DNMTs could suppress tumorigenesis and tumor growth by regulating FOXO3a/FOXM1/SOX2 signaling." (PMID 31296961, 2020). "Tumor suppressor genes may be epigenetically silenced by both DNMT1 and DNMT3B39,40." (PMID 31624299, 2019). "We then asked whether DNMT1 expression could also be relevant to tumor prognosis." (PMID 28036297, 2017). "Thus, overexpression of the major DNMT, DNMT1, may result in accumulated hypermethylation of DNA for tumor-related genes." (PMID 24592273, 2014). "Thus, studies are ongoing in our laboratory to identify a DNMT1/protein-x-including complex promoting the methylation-induced silencing of the tumor suppressor gene without being implicated in the methylation-induced silencing of oncogenes." (PMID 23809695, 2013). "In conclusion, this study has provided epigenetic evidence that promoter hypermethylation of all three important GL-associated genes, DNMT1, MGMT and EGFR may play a role in GL progression and the inactivation of these genes is stable even as concerns tumour recurrence." (PMID 22264301, 2012). "Thus, RNAi-mediated DNMT1 depletion in different tumor cells could induce demethylation of various tumor suppressor genes and enhance re-expression." (PMID 21999220, 2011). "In this study, we aimed to explore the roles of DNMT1, G9a, and UHRF1 proteins in this tumor by evaluating their expression in human PDAC tissue specimens." (PMID 39810240, 2025). "Expression overlays of six RNA modification genes selected by the LASSO Cox model (DNMT1, DNMT3A, HNRNPC, IGF2BP2, NSUN5, and ZC3H13) demonstrated variable distribution across the tumor microenvironment." (PMID 40565233, 2025). "The high expression of DNMT1 will enhance the phosphorylation of Akt in hepatoma cells and activate the PI3K-Akt pathway to promote tumor growth." (PMID 41335282, 2025). "The individual correlation of DNMT1, G9a and UHRF1 tumor expression with clinical-pathological variables revealed significant association with specific events, such as tumor stage or microvascular invasion." (PMID 39810240, 2025). "Integrated transcriptomic and methylation analyses further underscored the pivotal contribution of the DNMT1–RASSF1A axis in gene regulation and tumor progression." (PMID 41381440, 2025). "DNTM1 (DNA methyltransferase 1) is a critical epigenetic regulator, frequently upregulated in CRC, where it contributes to tumor suppressor gene silencing and chemotherapy resistance." (PMID 41319168, 2025). "DNMT1 and DNMT3A are generally upregulated, contributing to the aberrant hypermethylation of certain genes that are involved in both tumor suppression and resistance to drugs." (PMID 40191732, 2025). "Another compound, C02S, demonstrated strong inhibitory activity against DNMT1, DNMT3A, DNMT3B, and HDAC1, leading to apoptosis, cell cycle arrest, reduced angiogenesis, and decreased tumor proliferation in vitro and in vivo." (PMID 40358164, 2025). "LINC00337 promotes the development of tumours and angiogenesis in CRC by recruiting DNMT1 to suppress CNN1." (PMID 40387409, 2025).
tumor (continued). "Proteomic profiling further revealed its impact on multiple oncogenic and tumor-suppressive proteins, with notable upregulation of SERPINB2, KIT, and NOTCH1, alongside downregulation of COX2, DNMT1, MAPK1, AKT1, MKI67, EP300, and SMC1A." (PMID 41321870, 2025). "The NEAT1-EZH2/DNMT1 axis functions through NEAT1 binding to EZH2 or DNMT1, leading to silencing of p21 and DUSP4 by H3K27me3 or DNA methylation, facilitating tumor immune evasion and chemotherapy resistance." (PMID 41394878, 2025). "In AT/RT, DNA hypermethylation is frequently observed partially due to DNMT1 and DNMT3A upregulation, and DNMT inhibitors impaired tumor growth in vitro and in vivo." (PMID 40599851, 2025). "Beyond this, RX-3117 has been shown to inhibit DNA methyltransferase 1 (DNMT1), leading to DNA hypomethylation and the reactivation of tumor suppressor genes." (PMID 40702552, 2025). "The epigenetic reactivation of EphA7 via dCas9-TET1 reduced tumor growth and enhanced sensitivity to chemo-, radio- and immunotherapy by modulating SP1/DNMT1 and PI3K/AKT signalling." (PMID 41403730, 2025). "The interaction between G6PD, DNMT1, and BCAT1 in tumors presents an opportunity to develop new treatment methods that target tumor metabolism." (PMID 41462671, 2025). "In this manner, miR‐148a exhibits tumour‐suppressive properties in UCCB, and the miR‐148a/DNMT1 axis holds promising potential as an innovative therapeutic approach for addressing this particular malignancy." (PMID 40387409, 2025). "GSEA analysis indicated that DNMT1, a DNA methyltransferase, exhibited the highest enrichment score, and differential genes were also enriched in the DNA methylation pathway, suggesting that C1q may regulate tumor cell DNA methylation through DNA methyltransferases (DNMTs)." (PMID 40171991, 2025). "The high expression of DNMT1, DNMT3A, and DNMT3B correlates with low overall survival rate, increased tumor size, and lymph node metastasis in TNBC patients." (PMID 40427627, 2025). "The inverse correlation between DNMT1 and DACH1 expression highlighted the potential role of DNMT1 in silencing tumor suppressor genes DACH1 through epigenetic mechanisms." (PMID 40370966, 2025). "Compound (R)-23a, a dual DNMT1/HDAC inhibitor, has shown potent inhibition of both targets, effectively reactivating tumor suppressor genes and suppressing tumor growth in xenograft models." (PMID 40358164, 2025). "Combined targeting of FGFR and DNMT1 prevented induction of PDGFR, enhanced pulmonary tumor regression, slowed tumor recurrence, and prolonged survival." (PMID 40185706, 2025). "The consequent rise in DNMT1 hypermethylates the CpG-rich CDH13 promoter, thus blocking T-cadherin tumor-suppressive activity." (PMID 40649905, 2025). "We aimed to investigate the relationship between DNMT1, miR-152-3p, and SOS1, which collectively regulate self-renewal and tumor growth in NSCLC cells." (PMID 38622665, 2024). "The overexpression of UHRF1 repressed the transcription of such tumor-suppressor genes as CDKN2A, BRCA1, and CDH1 through DNMT1-mediated DNA methylation." (PMID 38725075, 2024). "Both DNMT1 knockdown and combined PI3K and CDK inhibition led to increased levels of glycolysis in tumor tissues, as indicated by increased numbers of PFK- and PKM2- positive cells." (PMID 38755637, 2024). "In this study, we revealed DNA damage, TET2 upregulation, demethylation, and re-expression of tumor suppressors on the underlying mechanism of DNMTi anticancer activity and resistance, particularly in the context of a lower dose (0.5 μM) of DNMTi, in the presence and absence of the DNMT1 gene." (PMID 39057134, 2024). "In contrast, DNMT1 and DNMT3B were unchanged with only one ALCL tumor, T3, showing a significant increase in transcript levels." (PMID 38464090, 2024). "CircFOXP1 recruits DNMT1 to hypermethylated the promoter of FOXP1, thereby inhibiting the expression of FOXP1, and ultimately facilitating tumor progression in colon cancer." (PMID 38745044, 2024).